CX3CR1 (C-X3-C motif chemokine receptor 1)
Diseases named in the same sentence as CX3CR1 in open-access papers (continued):
Sharing a sentence is not in itself a finding about the gene and the disease.
tumor (continued). "In this patient, consistent with a remarkable expansion of PB CX3CR1+ CD8+ T cells, single-cell profiling of longitudinal circulating T cells revealed effective early on-treatment differentiation and expansion of effector T cells that includes tumor resident T-cell repertoires." (PMID 37009132, 2023). "This indicated complete tumor rejection in the majority of the UBC-GFP cohort, which was contrary to our expectations given that 100% (9 of 9) of tumors took in another tolerized strain: Cx3cr1-GFP;CCR2-RFP mice, with final tumor burden similar to that of NOD-SCID mice (p = 0.78)." (PMID 36637515, 2023). "Tumours from gp130F/F stomachs were dissected, disaggregated and sorted by flow cytometry into three populations: gastric epithelial cells (E-cadherin+/CD45−), macrophage (Mφ) enriched immune cells (CD45+/CD11b+/SSClow/CX3CR1+/CD64+/MHCII+) and Mφ depleted immune cells (CD45+/Mφ depleted)." (PMID 35677533, 2022). "Due to the limitation in single cell numbers that could be isolated from the lung and the bone marrow, CX3CR1 expression on lung and bone marrow tumor cells was not analyzed." (PMID 34070094, 2021). "Interestingly, a previous study observed that CX3CR1 ectopic expression improved the recruitment of adoptively transferred T cells toward CX3CL1-generated cancers, leading to the augmentation of T-cell infiltration and reduction of tumor growth." (PMID 35140706, 2021). "In contrast to the soluble variant, the membrane located CX3CL1 with its physiological function as adhesion molecule promotes stronger adhesion of leucocytes to CX3CR1-positive cells, and therefore, might enhance T cell killing or NK cell mediated ADCC on trastuzumab coated BC tumor cells." (PMID 34070094, 2021). "Contrary to our results, a previous study suggested that CX3CR1 (lack of the allele I249) might play a limited or insignificant role in CRC, and plasma FKN/CX3CL1 does not appear to be a valuable tumor marker in CRC." (PMID 35140706, 2021). "Therefore, we speculate that besides promoting the invasion directly by affecting on tumour cells, in vivo injection of CX3CL1 may also be involved in the recruitment of M2 macrophages with high expression of CX3CR1." (PMID 33191645, 2021). "However, differences in T and NK cell maturation, or in PD-1 and CX3CR1 expression in spleen or tumor cells were not measurable between MDA-MB-453empty- and MDA-MB-453CX3CL1-based HTM or between the treatment groups." (PMID 34070094, 2021). "Moreover, in the CX3CR1-GFP mouse, we found that microglia within the tumor expressed TSPO." (PMID 31963507, 2020). "Of note, this consideration could also explain the fact that the slightly difference in small intestine tumor formation between APC+/min-CX3CR1-/- and APC+/min-CX3CR1+/- detected by both in vivo and ex vivo optical imaging was not confirmed by histological analysis (data not shown)." (PMID 30140377, 2018). "Tumor burden at the spleen was not affected by downregulation of CX3CR1 alone." (PMID 29712888, 2018). "Based upon these findings, we have proposed a model whereby the CX3CR1/CX3CL1 axis may contribute to interactions between CLL cells and tumor microenvironment by increasing CXCL12-mediated attraction of leukemic cells to NLC and promoting directly adhesion of CLL cells to NLC." (PMID 24799766, 2014). "Furthermore, in CX3CR1−/− mice with intracranial gliomas, the number of infiltrated TAMs was similar to that in CX3CR1+/− mice, along with a slight increase in tumor growth in CX3CR1−/− mice, suggesting that microglia has little contribution in TAM infiltration and the GBM tumor growth." (PMID 24675569, 2014). "Together with the decreases in Tim-3 and CX3CR1 levels in pNK cells after interaction with MCF-7 spheroids, these findings may indicate the involvement of the Tim-3/galectin-9 and CX3CR1/CX3CL1 pathways in the regulation of the cytotoxic response of pNK cells to MCF-7 tumor cells in the 3D model." (PMID 39457710, 2024).
tumor (continued). "However, CX3CR1+ subsets of CD90.1+ CD8+ Pmel-1 T cells were present in the tumors of FTY720-treated mice, suggesting that differentiation of CX3CR1+ CD8+ T cells occurs in the tumor and does not require the migration of CX3CR1− CD8+ T cells to secondary lymphoid organs." (PMID 38881188, 2024). "Interestingly, CX3CR1 and STAT3 have been reported to positively cooperate in modulating the immune interaction between monocytes and smooth muscle cells, indicating this observed signal may be tumor cell-autonomous." (PMID 27855189, 2016). "In MFC tumor-bearing mice, CX3CR1 expression was markedly up-regulated in MDSCs and PMN-MDSCs within the spleen and tumor tissues compared to the spleens of naïve mice, whereas no significant changes were observed in M-MDSCs." (PMID 41280721, 2025). "A linear regression analysis revealed that tumor levels of TNC and CCL2 each correlated with myeloid cell markers, including F4/80 (ADGRE1), CSFR1,and CX3CR1, but not with CCR2, with a higher correlation of TNC than CCL2 at the 3 week time point." (PMID 37176074, 2023). "At 24h post-injection, CX3CR1-GFP+CD115+ monocytes were detected in the lungs and in the tumor-draining mediastinal LNs, but not in the control inguinal LNs." (PMID 37426658, 2023). "Inspection of the data of De Kegel and Ryan, 2019 shows that ACKR3, CX3CR1, TBXA2R were not assigned to the essential category in any of the 558 tumor cell lines tested." (PMID 33427197, 2021). "Although these CX3CR1+ CD8+ T cells may remain in circulation and not infiltrate the tumor microenvironment (TME) in the absence of CX3CL1 production, their presence in peripheral blood may still serve as a valuable indicator of therapeutic response." (PMID 41149503, 2025). "Activation of non-classical monocytes through CX3CR1 leads to the upregulation of CCL3, CCL4, and CCL5 chemokines, resulting in the recruitment and activation of anti-tumoral NK cells, which contribute to cancer cell death, while this monocyte subset is not able to directly kill tumor cells." (PMID 41440002, 2025).
infection (167 papers, 2009 to 2026). The state of being infected such as from the introduction of a foreign agent such as serum, vaccine, antigenic substance or organism. "The interaction between CX3CL1 and CX3CR1 plays a crucial role in the immune response to RSV infection because mice genetically deficient in CX3CR1 develop more severe cases of infection." (PMID 39337288, 2024). "The M2 infection module revealed Chil3, Il4, Cx3cr1, Emr1 and Ccl2 as hubs, while module M6, associated with vaccination, disclosed Prf1, Klrc1, IFN-γ, Ncr1 and Tbx21 as hub proteins." (PMID 39563428, 2024). "CX3CR1 is expressed in epithelial cells of both the upper and lower respiratory tract, and CX3CR1-positive cells were more susceptible to infection." (PMID 40295855, 2024). "C. rodentium-infected animals harbouring IL-23-deficient CX3CR1+ cells acutely succumb to infection." (PMID 25761673, 2015). "To test this hypothesis, we performed a rescue experiment, where we administered recombinant IL-18 (rIL-18) at 10μg/kg or PBS to Cx3cr1+Casp1 deficient mice at 1 hour post-infection and on days 1, 3, 5, and 7 post-infection." (PMID 39446964, 2024). "In addition, markers (TLR4, CD68, Tyrobp and Cx3cr1) associated with microglial activation were significantly upregulated post infection." (PMID 38093309, 2023). "Therefore, the interaction of RSV F with BCRs on the surface of nBregs leads to increased expression of CX3CR1 on the surface of the cells, making them susceptible to direct infection." (PMID 37896776, 2023). "Also, a TEM cell cluster expressing high levels of Ly6C and CD127 (Li cluster 1) associated to LCMV Armstrong was detected in the liver, whereas liver KLRG1+CX3CR1+NKG2A+ TEM cells (Li cluster 8) associated predominantly to MCMV-GP33 infection." (PMID 33458613, 2021). "For example, subcutaneous infection of CX3CR1-deficient mice limited salivary gland dissemination." (PMID 30037007, 2018). "A previous report has implicated CX3CR1+ DC in control of VACV following an intranasal infection." (PMID 28614386, 2017). "Furthermore, animals with an IL-12/23 mutation restricted to CX3CR1+ cells succumbed to the infection." (PMID 25761673, 2015). "CX3CR1 is a chemokine receptor expressed on respiratory epithelial and immune cells and has been identified as a host factor important for infections with respiratory syncytial virus (RSV)." (PMID 42043252, 2026). "Compared with the untreated AMNV mice, the CX3CR1+ NK cell-treated mice had significantly lower bacterial loads and less injury to the lung tissue after infection." (PMID 41532069, 2026). "FMT increased the percentage of CX3CR1+ NK cells in the lungs of these mice, restored the disordered microbiota and metabolites, and alleviated the lung injury induced by infection." (PMID 41532069, 2026). "In response to either Aβ pathology or MA10 infection, microglia shared only four significantly down-regulated DEGs (Csf1r, P2ry12, Cx3cr1, Hexb), all of which are signature microglial homeostatic markers." (PMID 41497643, 2025). "In the lung at 4 weeks post-infection, accumulation of Ly6Cpos macrophages and DCs declined by more than 80% in CCR2-deficient (Ccr2RFP/RFP) and DKO mice, while CX3CR1-deficient (Cx3cr1GFP/GFP) mice had preserved trafficking relative to Het mice." (PMID 40497732, 2025). "Since microglia disperse away from Cn H99 cryptococcomas as the infection progresses, CX3CR1-EGFP mice were also i.c.-infected with H99 or cap59 cryptococci and their brain tissues were imaged with confocal microscopy at 7-dpi." (PMID 40038673, 2025). "At the same time, Cx3cr1 (C3 marker) expression continued to exhibit an upward trend at weeks four and six post-infection." (PMID 40244063, 2025). "Some studies additionally described an effector-like CX3CR1 + population arising late during the infection also present in our late samples from 14 and 21 dpi." (PMID 40971956, 2025).
infection (continued). "It is also not known whether deficiency of MAVS signaling of long-lived CX3CR1+ CNS cells might affect the outcome of T-cell responses due to potential differences in the pool of presented epitopes that would drive cross-presentation from BAMs in our infection model." (PMID 40619428, 2025). "C3 (Cx3cr1+NK) and C4 (Thy1+NK) increased at week four post-infection, and other subsets decreased continuously." (PMID 40244063, 2025). "In further receptor independent infection experiments using 10 and 100 μM of antagonist for CX3CR1, human microglial cells at 2dcc displayed reduced cell death levels in presence of antagonist in a dose dependent fashion." (PMID 40384979, 2025). "Viral G protein binding is specific, as treatment with the anti-CX3CR1 antibody decreases infection." (PMID 39337288, 2024). "At day eight post-infection, we performed ELISAs on the serum and found that Cx3cr1+Casp1 KO mice had decreased IFN-γ levels, comparable IL-12 levels, and decreased IL-18 levels compared to WT mice." (PMID 39446964, 2024). "Disruption of IFNλ signaling specifically in CX3CR1+ cells protected against mortality during lethal super-infection as compared to Cre- littermate controls." (PMID 39178311, 2024). "Among the RSV proteins, the G protein plays a crucial role in infection because its CX3C motif allows the virus to interact with the chemokine receptor CX3CR1." (PMID 39337288, 2024). "Here, we report that Salmonella enters the bloodstream through intestinal CX3CR1+ macrophages during early infection." (PMID 38528181, 2024). "Recent studies have shown that CX3CR1+ myeloid cells are involved in both Th17 and regulatory T-cell responses to infection in the gut." (PMID 39355243, 2024). "Virus-specific memory CX3CR1+CD8+T cells are increased during infection, but only a small number are present in the chronic infected state." (PMID 38674036, 2024). "We infected Cx3cr1cre/+ x Caspase 1 fl/fl (Cx3cr1+Casp1 KO) and Cx3cr1+/+ x Caspase 1fl/fl (WT) littermate controls with 10 cysts Me49 and at eight days post infection we harvested tissues." (PMID 39446964, 2024). "CX3CR1+ macrophages were also the major cell population harboring intracellular Salmonella shortly after infection." (PMID 38528181, 2024). "This analysis confirmed that during infection there was an upregulation of both Cd79a+Il10+ Bregs (p < 0.02, Mann–Whitney test) and Cx3cr1+Il10ra+ microglia (p < 0.01, Mann–Whitney test)." (PMID 38594373, 2024). "We employed inducible CX3CR1-specific conditional IFNLR1 knockout mice to determine if IFNλ acts directly on these cells during super-infection." (PMID 39178311, 2024). "The soluble form of the RSV G-protein, when binding to CX3CR1, acts as a competitive antagonist ligand, interfering with the chemotactic responses of immune cells and preventing their recruitment to the site of infection." (PMID 39337288, 2024). "In this work, we discovered that within 1 h after infection, Salmonella have been observed to accumulate in CX3CR1+ macrophages that surround the microvessels in the villi of the small intestine." (PMID 38528181, 2024). "When cells are infected with a mutant RSV that has an insertion in the CX3C motif of the G protein or when cells are treated with an anti-CX3CR1 antibody prior to infection with wild-type RSV, the induction of cytokines is decreased." (PMID 39337288, 2024). "After these drops, the relative frequencies of CX3CR1+ cells among the F4/80+ macrophages increased to the state before infection." (PMID 39355243, 2024). "The G protein plays a critical role in virus entry into the host cells and its CX3C motif interacts with the human chemokine receptor CX3CR1 to induce infection." (PMID 37993935, 2023). "The results indicated that the expression level of miR-709 increased over time after infection and that the expression levels of circStrbp and CX3CR1 decreased over time after infection." (PMID 38249464, 2023).
infection (continued). "At days 10 and 30 post-infection, splenocytes were collected and the expression of CX3CR1 on KO and WT OT-I cells was identified using flow cytometry." (PMID 37414528, 2023). "Although we were not able to characterize T cell subsets in detail in the chickens because of limited antibody availability, we found that memory CD8+ T cells and CX3CR1 expression were promoted by SCFA administration during infection." (PMID 37865711, 2023). "The findings indicate that the changes in circRNA-miRNA in the early stage of infection can regulate the expression of CX3CR1 and affect the early stage of virus infection." (PMID 38249464, 2023). "After 10 days of infection, the absolute number of CD11b+ CX3CR1+ macrophages was significantly decreased in the intestine of C. auris infected mice compared to C. albicans-infected groups." (PMID 37114044, 2023). "The proportion of CD45int cells in CX3CR1‐GFP+ cells tended to decrease with time of infection (p = 0.0007), while the proportion of CD45high cells in CX3CR1‐GFP+ cells increased (p = 0.0023)." (PMID 34766463, 2022). "IF staining of brainstem tissue sections confirmed that CX3CR1‐GFP+ cells expressed PD‐L1 on the 7th day after infection." (PMID 34766463, 2022). "Several groups used reporter mice to monitor changes CX3CR1 expression during infection with different pathogens and found that terminally differentiated TEFF cells expressed KLRG1 and CX3CR1 at high levels." (PMID 35942952, 2022). "IF staining of brain tissue sections confirmed that PD‐L1 was expressed in CX3CR1‐GFP+ cells on the 7th day after infection, and the CX3CR1‐GFP+ cells were close to PD‐1+ cells, while few PD‐1+ or PD‐L1+ cells were found in the normal brain (data not shown)." (PMID 34766463, 2022). "IF staining also indicated that the quantity of Ki67+CX3CR1‐GFP+ cells increased after PbA infection (p = 0.0077), while it was very low in the physiological brain (data not shown)." (PMID 34766463, 2022). "The IMs in lethally infected macaques uniformly expressed CCR2 and CX3CR1, indicating they were likely recruited from the vasculature in response to infection." (PMID 35271686, 2022). "To investigate the possibility of microglia trafficking T. gondii in the brain, we implanted cranial windows on CX3CR1-GFP mice prior to infection with tdTomato-expressing T. gondii." (PMID 36445695, 2022). "As observed during infection the levels of the differentiation markers CX3CR1 and KLRG1 were reduced and the expression of CTLA-4 increased in T cells from immunized Vhl cKO mice." (PMID 36064840, 2022). "This was also evident in a vaccination setting, as MPT70 immunization induced the biggest reduction of CX3CR1+KLRG1+ T cells after H37Rv::mpt70high infection." (PMID 33879592, 2021). "Infection with an MCK-2 mutant virus results in reduced recruitment of patrolling (CX3CR1+) and inflammatory (CCR2+) monocytes to the site of infection, a reduced patrolling monocyte-associated viremia, and reduced viral titers in the salivary gland." (PMID 33508041, 2021). "G’s binding to CX3CR1 facilitates the infection of primary human airway epithelial cells and suggests that CX3CR1 is a receptor for the infection of these cells." (PMID 34372490, 2021). "Over the course of infection, the total microglia population progressively downregulated CX3CR1, F4/80, TMEM119 and CD68, and progressively upregulated CD45." (PMID 34311763, 2021). "This is relevant because the G protein CX3C motif competes with FKN for binding to CX3CR1 and affects antiviral CX3CR1+ cells trafficking to the site of infection." (PMID 33672319, 2021). "G binding to CX3CR1 in primary human airway epithelial cells (pHAECs) facilitates the infection of these cells, and CX3CR1 is considered a receptor for the infection of these cells." (PMID 34372490, 2021).